HSCB (HscB mitochondrial iron-sulfur cluster cochaperone)
Description:
[Iron-sulfur cluster co-chaperone protein HscB, mitochondrial]: Acts as a co-chaperone in iron-sulfur cluster assembly in mitochondria. Required for incorporation of iron-sulfur clusters into SDHB, the iron-sulfur protein subunit of succinate dehydrogenase that is involved in complex II of the mitochondrial electron transport chain. Recruited to SDHB by interaction with SDHAF1 which first binds SDHB and then recruits the iron-sulfur transfer complex formed by HSC20, HSPA9 and ISCU through direct binding to HSC20. Plays an essential role in hematopoiesis (By similarity). [Iron-sulfur cluster co-chaperone protein HscB, cytoplasmic]: Acts as a co-chaperone in iron-sulfur cluster assembly in the cytoplasm. Also mediates complex formation between components of the cytosolic iron-sulfur biogenesis pathway and the CIA targeting complex composed of CIAO1, DIPK1B/FAM69B and MMS19 by binding directly to the scaffold protein ISCU and to CIAO1. This facilitates iron-sulfur cluster insertion into a number of cytoplasmic and nuclear proteins including POLD1, ELP3, DPYD and PPAT.
Synonyms: DNAJC20; HSC20; Jac1; SIDBA5
Tractability: PROTAC: ubiquitination databases record sites on it; its protein half-life has been measured.
Gene: Protein-coding gene on chromosome 22 (28,742,039 to 28,757,522, forward strand). Ensembl gene ENSG00000100209.
Subcellular location: Cytoplasm (Iron-sulfur cluster co-chaperone protein HscB, cytoplasmic); Mitochondrion (Iron-sulfur cluster co-chaperone protein HscB, mitochondrial)
Subcellular location (Human Protein Atlas): Cytosol; Mitochondria; Nucleoplasm
Pathways (Reactome):
Metabolism: Complex I biogenesis; Complex III assembly; Mitochondrial iron-sulfur cluster biogenesis
Protein localization: Mitochondrial protein import
Gene Ontology:
Molecular function: identical protein binding; protein binding; ATPase activator activity; protein-folding chaperone binding
Biological process: iron-sulfur cluster assembly; [2Fe-2S] cluster assembly; primitive erythrocyte differentiation; primitive hemopoiesis; protein complex oligomerization
Cellular component: cytoplasm; cytosol; mitochondrion
Genetic constraint (gnomAD): Loss-of-function variants: 9 observed, 17.3 expected, observed/expected ratio (o/e) 0.52, 90% interval 0.31 to 0.91. The upper end of that interval is the gene's LOEUF score, 0.91, which puts it in group 3 of 6, group 1 being the genes least tolerant of losing a copy. Missense variants: 205 observed, 212.76 expected, observed/expected ratio (o/e) 0.96, 90% interval 0.86 to 1.08. Synonymous variants: 83 observed, 85.75 expected, observed/expected ratio (o/e) 0.97, 90% interval 0.81 to 1.16.
Homologues: Orthologues: chimpanzee HSCB (98% identical), macaque HSCB (97% identical), dog HSCB (86% identical), rabbit HSCB (84% identical), pig HSCB (83% identical), guinea pig HSCB (81% identical), mouse Hscb (73% identical), rat Hscb (61% identical), tropical clawed frog hscb (42% identical), zebrafish hscb (38% identical), Drosophila melanogaster Hsc20 (28% identical), Caenorhabditis elegans dnj-15 (26% identical).
Diseases named in the same sentence as HSCB in open-access papers:
HSCB is named in the same sentence as 16 diseases in open-access papers, as found by Europe PMC text mining. Sharing a sentence is not in itself a finding about the gene and the disease. The quoted sentences say what the papers report.
neutropenia (1 paper, 2024). A decrease in the number of neutrophils found in the blood. "Our research was initially inspired by the findings that a CSA proband carrying heterozygous HSCB mutations developed moderate thrombocytopenia and mild neutropenia." (PMID 38757931, 2024).
cancer (8 papers, 2019 to 2025). A tumor composed of atypical neoplastic, often pleomorphic cells that invade other tissues. "Previous studies showed GLRX3, GLRX5, WRNIP1, THOP1, and HSCB were all regulators of various cancer occurrence and progression." (PMID 34078439, 2021).
HSCB also shares sentences with these, for which no sentence is quoted: breast carcinoma (7 papers); tumor (6); congenital sideroblastic anemias (1); diabetes (1); enteritis (1); Friedreich ataxia (1); gastric cancer (1); hepatocellular carcinoma (1); infection (1); lung carcinoma (1); non-small cell lung carcinoma (1); Sepsis (1); Thrombocytopenia (1); triple-negative breast carcinoma (1).